TNF (tumor necrosis factor)
Diseases named in the same sentence as TNF in open-access papers (continued):
Sharing a sentence is not in itself a finding about the gene and the disease.
tumor (continued). "It was recently demonstrated in a transplantable tumor model that TNF–TNFRII axis may control the survival of MDSCs through upregulation of cellular FLICE-inhibitory protein (c-FLIP), leading to the inhibition of caspase-8 activity." (PMID 27148266, 2016). "Moreover, the intracellular production of IFN-γ and TNF-α in the tumor-infiltrating OT-I and OT-II cells in mice treated with the combination of ascophyllan and OVA were substantially increased compared to those treated with ascophyllan or OVA alone." (PMID 27008707, 2016). "TNF-α is a cytokine primarily produced by macrophages and activates the extrinsic apoptosis pathway following its binding to cell surface death receptors on tumor cells." (PMID 26799286, 2016). "HMGB1 is a key mediator of chronic inflammation in MM, leading to Nalp3 inflammasome activation, macrophages accumulation, interleukin (IL)-1β and TNF-α secretion, and thus to activation of the NF-κB pathway, which increases cell survival and tumor growth after asbestos exposure." (PMID 27171110, 2016). "For example, combinatorial treatment of low doses of interleukin-2 (IL-2) and TNF-α in NSCLC patients has resulted in enhanced tumor regression, making these pro-inflammatory cytokines an attractive choice of therapeutic agent to be used in immunotherapy to treat cancer." (PMID 26927069, 2016). "In addition, consistent with what was observed in irradiated tumor cell lines in vitro, Fas and TNFα are up-regulated by radiation in the tumor microenvironment." (PMID 27014915, 2016). "Furthermore, TNF-α and IL-17A are thought to have synergistic tumor promoting properties when expressed together in CRC cells, whereby these cytokines stimulate glucose metabolism and growth factor production." (PMID 27014625, 2016). "Additionally, in a similar manner to that in wounds, neutrophils secrete cytokines including IL-6, IL-8, TNF-α, and GM-CSF, enhancing angiogenesis and tumor progression." (PMID 26884644, 2016). "Together, these results suggest that TNFα secretion by B cells may regulate tumor growth through production of IL-10+ Bregs, which in turn attenuate CD8+IFN-γ+ T cell responses." (PMID 27437104, 2016). "Moreover, activity tests showed that Se-CEPS improved the immune organ index of CT26 tumor-bearing mice and increased the TNF-α and IL-2 levels in serum." (PMID 27347005, 2016). "The enhanced immune function, as evidenced by increase of IL-2/-6, and TNF-α, peripheral white blood cells counts, thymus and spleen index following the polysaccharides treatment, might delineate these anti-tumor activities." (PMID 26978396, 2016). "Additionally, signaling pathways such as the nuclear factor κB (NF-κB), transforming growth factor β (TGFβ), and tumor necrosis factor α (TNFα) can promote further cytokine release in the tumor environment, and impact tumor progression greatly." (PMID 27270649, 2016). "We hypothesize that the high levels of proinflammatory mediators present in the supernatants, particularly TNF, induced tumor cell death." (PMID 27119077, 2016). "Thus, for purposes of sensitizing tumor cells to the cytotoxic actions of TNFR1 agonists such as TNF and LT-α, the proteins cIAP1 and cIAP2 are critical targets." (PMID 27617834, 2016). "Although TNF-α was first identified as a soluble factor capable of inducing tumour necrosis, various mechanisms have been described by which TNF-α may promote cancer growth, invasion, and metastasis." (PMID 26881177, 2016). "As TNF is known to have anti-tumour effects, there were initial concerns that TNF inhibition could increase cancer incidence." (PMID 27906042, 2016). "Due to their sheddase activity cleaving off transmembrane proteins, including EGF-receptor ligands, Fibroblast growth factor receptor, CD44, E-cadherin, N-cadherin, Notch, L1, and TNF-α, they regulate paracrine and autocrine signaling pathways involved in tumor growth and progression." (PMID 27542270, 2016).
tumor (continued). "FAT10 expression is induced by interferon (IFN)-γ and tumor necrosis factor α (TNFα) in tumor cells, which indicate IL-8-mediated receptors may sustain NFκB activity by a feedback system in chronic inflammatory-associated microenvironments such as in AH." (PMID 27019857, 2016). "The concentration of IL-2 and TNF-alpha are also differently regulated, which may result in enhancing the ability of tumor controlling for cancer patients." (PMID 27015629, 2016). "Moreover, through activation of NF-κB and STAT3, TNF-α can enhance epithelial-mesenchymal transition which are critical steps that allow polarized epithelial tumor cells to become mesenchymal like, enhancing cell migration and invasion." (PMID 27323816, 2016). "Also in human cells, NK cell-secreted IFNγ and TNF induce cross-presentation of tumor cell-derived antigens by monocyte-derived DCs, promoting the induction of a tumor-specific CD8 T cell response." (PMID 27446081, 2016). "The potent anti-inflammatory and anti-tumor effects of embelin were demonstrated by the findings that this agent dramatically reduced the infiltration of macrophages and decreased the expression of TNFα, IL-6, IL-1β, COX-2 and iNOS in colonic tissues." (PMID 26799669, 2016). "IFN-γ may function as a tumor promoter by stimulating the release of inflammatory mediators such as TNF-α that advance carcinogenesis." (PMID 26727596, 2016). "TNF-α was also expressed at the tumor site in the present case." (PMID 26951080, 2016). "Furthermore, MC were observed to inhibit tumor development, which was attributed to the release of pro-inflammatory cytokines and proteases such as TNF-α and tryptase." (PMID 26978404, 2016). "In the present study, we show that both apoptosis and necroptosis occur within the same tumor and that necroptosis may be the dominant pathway of cell death in TNF-treated RCC." (PMID 27362805, 2016). "It was widely accepted that the host-related inflammatory response plays an important role in tumorigenesis, tumor progression, and metastasis through recruitment of regulatory T lymphocytes and cytokines, including interleukin-1 (IL-1), IL-6, and tumor necrosis factor α." (PMID 26438061, 2016). "Indeed, it was previously shown that expression of globotriaosylceramide Gb3, which is considered as a tumor-marker of Burkitt’s lymphomas, is induced on endothelial cells by TNF and IL-1." (PMID 27916834, 2016). "Radiation-induced TNFα induces tumor cell death in an autocrine manner." (PMID 27014915, 2016). "Furthermore, gold nanospheres conjugated with tumor-necrosis factor also show high delivery efficiency to tumor-bearing mice." (PMID 27898016, 2016). "TNF-α induces the tumor immune response and cell differentiation, promotes the production of a variety of cytokines by mononuclear cells and T cells, and induce tumor cell apoptosis and directly kill tumor cells." (PMID 27881109, 2016). "In tumor cells the mechanism could differ somewhat, considering that caspases could be activated by TNFα or ROS generation, resulting in RNA disruption." (PMID 26911141, 2016). "Consider that anti-TNF-α treatments overcame chemoresistance vitro, and reduced the tumor promoting tumor stroma, we further hypothesized that anti-TNF-α treatments will synergize with the standard chemotherapy in pre-clinical models of PDAC." (PMID 27835602, 2016). "TNF neutralization by either of the two blockers, infliximab or etanercept, resulted in comparable reduction of tumor volume in hTNF KI mice and also correlated with reduced frequency of MDSCs, which may play a pro-tumorigenic role." (PMID 27148266, 2016). "Interestingly, it has recently been shown that synergic induction of COX-2 by IFN-γ and TNF-α limits type-1 immune response in tumor microenvironment by concomitant action of IL-10, NOS2, and Indoleamine 2,3-dioxygenase." (PMID 28018318, 2016). "In addition, the astrocytes encourage tumour growth by the secretion of cytokines, la heparanasa, neurotrophic factors, TNFα, TGFβ, IL6, etc." (PMID 28105072, 2016).
tumor (continued). "Finally, intra tumor TNFα and IFNγ level was significantly reduced in DDB1F/F, Alb-Cre+/−, IL6−/− mouse comparing to DDB1F/F, Alb-Cre+/− mouse." (PMID 27556180, 2016). "TNF-α may be involved in carcinogenesis through induction of proliferation, invasion, and metastasis because it may have both tumour-necrotic and tumour-promoting activities." (PMID 27547238, 2016). "However, a significant increase in the frequency of IL-17+TNF-α+ CD4+ T cells was observed in tumor tissue relative to adjacent uninvolved intestine (p < 0.05)." (PMID 27014625, 2016). "Tumor-associated macrophages and myeloid suppressive cells represent tumor-promoting immune cells together with their derived cytokines IL-6, IL1β, IL23 and TNFα." (PMID 27608835, 2016). "TNF‐α plays an important role in mediating chronic inflammation, and it is a key tumour promoter." (PMID 26945693, 2016). "To test physiologically relevant concentrations of TNFα and IL-6 in illness, we included two combinations containing both TNFα and IL-6 that reflected plasma levels measured in C26 adenocarcinoma tumour-bearing mice or Lewis Lung tumour-bearing mice respectively." (PMID 27207102, 2016). "Moreover, apoptotic rate in tumor cells of mice which received TNF-α preactivated MSCs plus irradiation was significantly higher than that of mice with single treatment of TNF-α preactivated MSCs (P < 0.01)." (PMID 27329316, 2016). "Supporting the protumorigenic roles of FcγRIIlow/− B cells, high infiltration of FcγRIIlow/− B cells in HCC tumours positively correlated with dysfunction of tumour-derived CD8+ T cells with impaired capacities for production of proinflammatory TNF-α and IFN-γ and cytotoxic granzyme B and perforin." (PMID 27853178, 2016). "To test this hypothesis, we evaluated the ability of clinically used TNF blockers to prevent transplantable tumor growth in mice." (PMID 27148266, 2016). "In ES 44% of MCT and 37% of MCTC expressed TNFα in the tumour islets." (PMID 27922077, 2016). "Here, we showed that exposure to TNFα and TGFβ, two factors commonly present in the tumor microenvironment that signal through distinct pathways, induced overt EMT in the Panc-1 cell line of human PDAC, reflected by EMT-like morphological, molecular, and functional changes." (PMID 27777765, 2016). "TNF-α and IL-1β are released into the tumor environment when TLRs are activated in tumor cells." (PMID 28116318, 2016). "Notably, TNFα, together with IFNγ, plays an important role in initiating the immune response by activating tumor-specific cytotoxic T cells." (PMID 27678372, 2016). "It has been proven in knockout mice that MMP-9 and the TNF-α are crucial for metastasis in the lung as in its presence, cancerous cells can become established because of abundant pulmonary vascularisation and grow as tumour nodules." (PMID 28105072, 2016). "Moreover, a significant increase was observed in IFN-γ (b) and TNF-α (c) secretion by B7-H3Bi-armed ATC over their unarmed ATC counterpart when ATC was co-cultured with B7-H3-positive tumor cell respectively (P < 0.05)." (PMID 27121051, 2016). "In addition to activating macrophages, in the tumor environment, TNF-α is able to promote angiogenesis." (PMID 27793032, 2016). "Both chemotherapy and TNF-alpha may induce a local inflammatory reaction within the tumor microenvironment and therefore may influence expression of PSME1." (PMID 27733900, 2016). "We found ~10-fold more tumor necrosis factor-α (TNFα) in tumor-infiltrating monocyte/macrophage-conditioned media compared with the conditioned media from naive monocytes/macrophages, suggesting TNFα as a possible candidate for the induction of S100A8 and S100A9." (PMID 27086923, 2016). "A growing number of in vivo and in vitro studies suggest that the levels of inflammatory factors present in tumor tissues and serum, including interleukin (IL)-6, tumor necrosis factor-α (TNF-α), IL-1β, IL-10, and transforming growth factor-β (TGF-β), are often higher in patients with HCC." (PMID 27658781, 2016).
tumor (continued). "Taken together, these data show that TNF neutralization might reduce tumor growth and MDSC accumulation in a transplantable MCA tumor model in mice." (PMID 27148266, 2016). "IL-6 induces the Janus kinase/signal transducer and activator of transcription (JAK/STAT) and MAPK pathways, stimulating cell proliferation and tumor progression, while TNF-α influences cancer angiogenesis, metastasis development and cell survival, growth, and differentiation." (PMID 27187365, 2016). "Low dose of TNFα could induce vessel remodeling and increase vessel perfusion, thereby enhancing drug accumulation in the tumor." (PMID 27342639, 2016). "Similarly, Huang and colleagues demonstrated inhibition of TNF-α-induced ICAM-1 expression along with inhibition of tumor cell (A549 cells) invasion and MMP-9 expression." (PMID 26823953, 2016). "Similarly, tumor antigen specific CD4+ Th1 cells attracted to the tumor microenvironment will secrete IL-2, TNF-α, and IFN-γ, creating an environment for enhanced activity of antigen presenting cells (APC)." (PMID 27766079, 2016). "The joint action of interferon-gamma and TNF-α may lead to cell cycle arrest in most cancers, however, this phenomenon requires the tumor to express sTNFR1." (PMID 26928194, 2016). "It has been suggested that TGF-β may reduce tumor lysis mediated by NK cells and stimulate the production of proinflammatory cytokines such as tumor necrosis factor alpha (TNF-α) and interferon gamma (IFN-γ)." (PMID 26983546, 2016). "Additionally, both TNF-α preactivated AD-MSCs and TNF-α preactivated MSCs plus irradiation significantly induced apoptosis in the tumor cells compared to the naïve AD-MSCs and naïve MSCs plus irradiation respectively (P < 0.01)." (PMID 27329316, 2016). "Moreover, the abundant of inflammation cytokines secreted by activated macrophages in the adipose tissue, such as TNFα, IL-6, etc., constitutes tumor microenvironment, which promotes tumor cell migration and invasion." (PMID 27247890, 2016). "Pro-inflammatory macrophages are generally characterized by the production of high levels of pro-inflammatory mediators, such as TNF-α, IL1-β, IL-6 or IL-12 and are associated with bacterial clearance and tumour cytotoxicity, being considered tumour suppressors." (PMID 27513864, 2016). "TNF-α has been shown to mediate anti-tumor immunity as well." (PMID 28536374, 2016). "Furthermore, BF-rTK + GCV showed to repress the inflammation of tumor through downregulating TNF-α expression." (PMID 27464624, 2016). "Furthermore, IFN-β can strengthen expression of host T cell receptors and surface MHC antigen expression, as well as tumor necrosis factor concentrations and other anti-tumor responses." (PMID 27029063, 2016). "Consistent with this, we also observed that high infiltration of FcγRIIlow/− B cells in HCC tumours positively correlated with increased dysfunction of CD8+ T cells with impaired capacities for production of proinflammatory TNF-α and IFN-γ and cytotoxic granzyme B and perforin." (PMID 27853178, 2016). "Another possible mechanism may involve the recently described ability of chemotherapy agents such as docetaxel and doxorubicin to induce TNFα production and release from tumor cells." (PMID 26911141, 2016). "Here we found that both TNF-α and IL-6 production by tumour cells is diminished upon Axl knockout." (PMID 28008921, 2016). "The inflammatory response that these stimulating factors initiate is followed by the release of important cytotoxic molecules such as reactive nitrogen intermediates (RNIs) and tumor necrosis factor (TNF)-α that can have an impact on the presence of tumor cells." (PMID 30974698, 2016). "This hypothesis is supported by the failure of RT-PCR to detect TNF-alpha transcripts in tumor biopsies before and after treatment as TNF-alpha has a role in lymphocytic migration." (PMID 27663515, 2016).
tumor (continued). "After treated with UA or NPs, there was an obvious decrease in expression of IFN-γ and TNF-α comparing with saline control group, implying drug-treated group could modify the immune system of tumor-burdened mouse into a good trend." (PMID 27469490, 2016). "Although TNF-α was initially found to induce cell death in some cancer types, recent studies have shown that it may also exert tumor-promoting activities such as the induction of transformation, proliferation, angiogenesis, invasion and metastasis." (PMID 27042827, 2016). "The chronic host inflammatory response in cancer patients elicits muscle degradation even in the face of adequate nutrition, and cytokines including IL-6 and TNF-α produced by the host immune cells in response to a tumor are major contributors to muscle wasting." (PMID 27064118, 2016). "Tumor necrosis factor alpha (TNF-α), a key pro-inflammatory cytokine that was first identified as a mediator of tumor cell death, is now also known to promote the tumor progression, proliferation, epidermal-mesenchymal transition (EMT), angiogenesis, invasion and metastasis." (PMID 26992854, 2016). "Tumor tissues from mice treated with clorgyline or NMI exhibited high numbers of macrophages and a significant increase in TNF-α expression, indicating that the macrophages present were likely to be proinflammatory cells, thus invovled in reduced tumor progression." (PMID 26871599, 2016). "In hypoxic areas, TAMs stimulate angiogenesis by secreting TGF-β, VEGF, granulocyte macrophage (GM)-CSF, TNF-α, IL-1, IL-6, and IL-8, promote tumor cell migration and invasion via matrix metalloproteinases (MMPs), TNF-α, and IL-1 and induce immunosuppression via TGF-β, PGE2, and IL-10." (PMID 27044404, 2016). "Both IFN-γ and TNF-α can thus play a dual role in tumor immunity." (PMID 28536374, 2016). "Moreover, exemplary compounds sensitize tumor cell lines to the cytotoxic activity of the cytokines TNF and lymphotoxin-α (LT-α), which utilize the TNFR1 complex to transduce signals into cells." (PMID 27617834, 2016). "Nevertheless, few reports indicate that TNF may also have an anti-tumor effect in CAC, possibly by providing early antibacterial protection in Il10−/− mice." (PMID 27148488, 2016). "On the other hand, TNF-alpha in the tumor microenvironment could attract myeloid cells in an IL-17-dependent manner and contribute to tumor-promotion." (PMID 27531373, 2016). "Moreover, the site of occurrence of tumors influences the role of TNF-α as pro- or anti-tumour agent." (PMID 27548121, 2016). "We further evaluated anti-tumor effects of anti-TNF-α treatments in PDAC." (PMID 27835602, 2016). "Indeed, IFN-γ and TNF-α are known to enhance NK cytotoxicity and macrophage phagocytosis of tumor cells." (PMID 27713158, 2016). "Interestingly, c-FLIP was present at high levels in untreated tumor cells and its expression levels are unaltered by TNF treatment." (PMID 27362805, 2016). "B16F10 tumours treated IT also showed increased levels of TNFα." (PMID 27412241, 2016). "We conclude that tumor clearance or growth retardation might benefit from the increased induction of TNF-α by aroA mutants." (PMID 27601574, 2016). "However, our study showed that CD3+CD56+ NKT-like cells in GC tumors displayed impaired effector function when stimulated, such as lower IFN-γ and TNF-α production than those in non-tumor tissues." (PMID 27409423, 2016). "On the other hand, TNF can disrupt tumor vasculature and induce cell apoptosis." (PMID 27057094, 2016). "The median density of all cells expressing TNFα (mast cells and other cells) in tumour islets of patients with an above median survival was also noted to be significantly greater (71.1 cells/mm2) than in patients with a below median survival (12.7 cells/mm2) (p = 0.0035)." (PMID 27922077, 2016).